LINC00942 (long independently transcribed non-coding RNA 942)
Gene: Long non-coding RNA gene on chromosome 12 (1,500,454 to 1,510,830, forward strand). Ensembl gene ENSG00000249628.
Diseases named in the same sentence as LINC00942 in open-access papers:
LINC00942 is named in the same sentence as 8 diseases in open-access papers, as found by Europe PMC text mining. Sharing a sentence is not in itself a finding about the gene and the disease. The quoted sentences say what the papers report.
breast carcinoma (8 papers, 2021 to 2025). "LINC00942 has been linked to prognosis and immune responses in hepatocellular and bladder cancers and promotes METTL14-mediated m6A methylation in breast cancer." (PMID 40034693, 2025). "LINC00942 has been reported as a tumor promoter in various cancers, including lung adenocarcinoma, breast cancer, and gastric cancer." (PMID 38353724, 2024). "LINC00942 acts as an oncogene in breast cancer that promotes cell proliferation and colony formation and inhibits cell apoptosis." (PMID 35685422, 2022). "Recent studies have shown that LINC00942 potentiated breast cancer cell proliferation and progression by affecting METTL14-mediated m6A methylation." (PMID 34987577, 2021). "It has been unveiled that LINC00942 serves as an oncogene by promoting METTL14-mediated m6A methylation in breast cancer." (PMID 34238292, 2021). "LINC00942 was reported to promote METT14-mediated M6A methylation and regulate the expression and stability of its target gene CXCR4 and CYP1B1 during the initiation and progression of breast cancer." (PMID 34760693, 2021).
gastric cancer (3 papers, 2023 to 2024). A primary or metastatic malignant neoplasm involving the stomach. "Moreover, LINC00942 has been implicated in promoting chemoresistance in gastric cancer by impeding the degradation of oncoprotein MSI2." (PMID 38589454, 2024).
lung adenocarcinoma (3 papers, 2022 to 2025). A carcinoma that arises from the lung and is characterized by the presence of malignant glandular epithelial cells. "For example, LINC00942 facilitates growth of lung adenocarcinoma by targeting miR-5006-5p to upregulate FZD1." (PMID 38353724, 2024). "Meanwhile, in lung adenocarcinoma, patients with higher LINC00942 demonstrated poor prognosis." (PMID 35550563, 2022).
lung carcinoma (1 paper, 2021). "LINC00942, LINC01116, SNHG4, MIR31HG, and LINC00460 had been known to be associated with tumor development and progression and drug resistance in various cancers including lung cancer." (PMID 35083132, 2021).
cancer (6 papers, 2016 to 2024). A tumor composed of atypical neoplastic, often pleomorphic cells that invade other tissues. "Linc00942 has been reported to be a tumor‐promoting factor in several cancers; however, the sequence of Linc00942 in previous studies was based on predictions." (PMID 39342418, 2024). "LINC00942 is rarely studied in cancer, and it is believed to promote the expression of GCLC, thereby causing poor prognosis for patients." (PMID 33585468, 2020). "Knockdown of Linc00942 reduces DNMT3a expression and genome‐wide DNA methylation while Linc00942 overexpression increased DNMT3a expression and correlated hypermethylation in cancer cells and primary tumour tissues." (PMID 37477089, 2023).
tumor (4 papers, 2021 to 2024). "The tumor volume and growth rate were significantly decreased after the knockdown of LINC00942 (p < 0.001, n = 5)." (PMID 38353724, 2024). "Moreover, the Fe2+ levels and intracellular lipid ROS levels in mouse tumor tissues showed a marked elevation, while the numbers of FOXP3+CD25+ and CD8+ Treg cells in tumors were reduced, which revealed that LINC00942 inhibits ferroptosis and induces immunosuppression (p < 0.001, n = 5)." (PMID 38353724, 2024).
LINC00942 also shares sentences with these, for which no sentence is quoted: bladder cancers (1 paper); colorectal cancer (1).